DPPA2 (developmental pluripotency associated 2)
Description:
Binds to target gene promoters, including NKX2-5 and SYCE1, but not GATA4, and may be involved in the maintenance of the active epigenetic status of these genes.
Synonyms: PESCRG1; CT100; ECAT15-2
Tractability: No criterion of Open Targets' tractability assessment is met for any kind of drug.
Gene: Protein-coding gene on chromosome 3 (109,293,788 to 109,316,517, reverse strand). Ensembl gene ENSG00000163530.
Subcellular location: Nucleus
Subcellular location (Human Protein Atlas): Nucleoplasm
Pathways (Reactome):
Developmental Biology: Zygotic genome activation (ZGA)
Gene Ontology:
Molecular function: protein binding; chromatin binding
Biological process: system development
Cellular component: nucleus
Genetic constraint (gnomAD): Loss-of-function variants: 26 observed, 35.95 expected, observed/expected ratio (o/e) 0.72, 90% interval 0.53 to 1. The upper end of that interval is the gene's LOEUF score, 1, which puts it in group 4 of 6, group 1 being the genes least tolerant of losing a copy. Missense variants: 361 observed, 381.09 expected, observed/expected ratio (o/e) 0.95, 90% interval 0.87 to 1.03. Synonymous variants: 113 observed, 127.12 expected, observed/expected ratio (o/e) 0.89, 90% interval 0.76 to 1.04.
Homologues: Orthologues: chimpanzee DPPA2 (99% identical), macaque DPPA2 (96% identical), pig DPPA2 (61% identical), rat Dppa2 (44% identical), mouse Dppa2 (43% identical), tropical clawed frog dppa2 (16% identical). Paralogues in human: DPPA4 (41% identical).
Diseases named in the same sentence as DPPA2 in open-access papers:
DPPA2 is named in the same sentence as 13 diseases in open-access papers, as found by Europe PMC text mining. Sharing a sentence is not in itself a finding about the gene and the disease. The quoted sentences say what the papers report.
non-small cell lung carcinoma (2 papers, 2018 to 2026). A group of at least three distinct histological types of lung cancer, including non-small cell squamous cell carcinoma, adenocarcinoma, and large cell carcinoma. "ECSA/DPPA2, also known as CT100, is a human embryonic antigen that is predominantly expressed in NSCLC (Non-small cell lung carcinoma) and also in other malignancies including melanoma, lymphoma, and in lung, liver and colorectal cancers." (PMID 29849983, 2018).
esophageal squamous cell carcinoma (1 paper, 2018). Esophageal squamous cell carcinoma (ESCC) is a type of esophageal carcinoma (EC) that can affect any part of the esophagus, but is usually located in the upper or middle third. "The viral particles were transducted to Esophageal Squamous Cell Carcinoma (ESCC) cell line (KYSE-30 cells) and the stable transducted cells were confirmed for ectopic expression of DPPA2 gene by real-time PCR." (PMID 29849983, 2018).
gastric cancer (1 paper, 2021). A primary or metastatic malignant neoplasm involving the stomach. "The original clinical studies reported that a high protein level of DPPA2 is implicated in lymphatic metastasis and further gastric cancer metastasis." (PMID 34721660, 2021). "As DPPA2 is elevated in cancer cells and implicated with cell metastasis in gastric cancer, we reasoned that the TF CTCFL functions on cell malignant behaviors in gastric cancer via targeting DPPA2." (PMID 34721660, 2021). "It was found that CTCFL and DPPA2 were highly expressed in cancer cases, which demonstrated that these two genes might be implicated with the cell characteristics in gastric cancer." (PMID 34721660, 2021). "As we had confirmed that CTCFL could positively mediate DPPA2, to clearly clarify the underlying mechanism in gastric cancer, rescue experiments were further conducted." (PMID 34721660, 2021). "In sum, this study finds that CTCFL and DPPA2 play an essential part in the malignant progression of gastric cancer, and their expression level may be associated with prognosis." (PMID 34721660, 2021). "We used bioinformatics analysis to know that CTCFL and DPPA2 were both differentially expressed in gastric cancer." (PMID 34721660, 2021). "The transcription factor CTCFL fosters cell proliferative, migratory, and invasive properties via activating DPPA2 in gastric cancer." (PMID 34721660, 2021). "But the specific molecular mechanism by which DPPA2 affects gastric cancer progression is a highly unmet need." (PMID 34721660, 2021). "Furthermore, rescue experiments were used to clarify the mechanism of CTCFL/DPPA2 in gastric cancer." (PMID 34721660, 2021). "In view of these, we could see that overexpressing CTCFL or DPPA2 promotively functions on cell behaviors, but the regulation between themselves or towards gastric cancer is unclear." (PMID 34721660, 2021). "CTCFL and DPPA2 were both highly expressed in gastric cancer cells, and high CTCFLL and DPPA2 could promote cell malignant behaviors." (PMID 34721660, 2021). "Taken together, it could be seen that DPPA2 played a promotive role in cell malignant phenotypes in gastric cancer." (PMID 34721660, 2021). "We described differential CTCFL and DPPA2 expression in gastric cancer tissues." (PMID 34721660, 2021). "Collectively, in gastric cancer, TF CTCFL activates DPPA2 to foster cell proliferation, migration, and invasion." (PMID 34721660, 2021). "In addition, high DPPA2 rescued the repressive impact of CTCFL silencing on the cell proliferation, migration, and invasion in gastric cancer." (PMID 34721660, 2021). "Meanwhile, our study confirms the targeted relationship between DPPA2 and CTCFL, which may help to develop a novel strategy towards gastric cancer prevention and treatment." (PMID 34721660, 2021). "Thus, we could conclude that DPPA2 overexpression suppressed the negative effect of CTCFL silencing on cell malignant phenotypes in gastric cancer." (PMID 34721660, 2021).
glioma (1 paper, 2024). A benign or malignant brain and spinal cord tumor that arises from glial cells (astrocytes, oligodendrocytes, ependymal cells). "They analyzed The Glioma French, the Cancer Genome Atlas (TCGA), and the Chinese Glioma Genome Atlas datasets, reporting that the expression of Twist 1 [a gene that stimulates the stemness markers such as BMI1, CRIPTO1, DPPA2, KLF4, and SOX2 in CSC] is related to a poor prognosis in GB patients." (PMID 39153092, 2024).
neuroblastoma (1 paper, 2021). Neuroblastoma (NB) is the most common solid, extracranial childhood tumor. "For example, DPPA2 knockdown exerts an inhibitory role in the proliferation of mouse stem cells and is able to decrease the metastasis of cancer stem cells in neuroblastoma cell lines." (PMID 34721660, 2021).
parasitic infection (1 paper, 2012). "An intriguing possibility would involve DPPA2 influencing both OvLV and parasitic infection through alterations in immune system development, since alterations in embryonic and/or white blood cell development could influence formation and/or maintenance of immune responses." (PMID 23082221, 2012).
cancer (8 papers, 2016 to 2026). A tumor composed of atypical neoplastic, often pleomorphic cells that invade other tissues. "The epigenetic priming factors developmental pluripotency-associated 2 and 4 (DPPA2/4) have crucial roles in early development and are implicated in cancer pathogenesis." (PMID 41862192, 2026). "We identified 30 cancer-specific normal-invariant genes, including Zic family members (ZIC1, ZIC4, and ZIC5), DPPA2, PRSS56, ELF5, and FGF18, most of which were cancer-associated genes." (PMID 39969322, 2024). "DPPA2 is differentially expressed in diverse cancers and can be used as a specific therapeutic target in some tumors, such as ovarian cancer, colon cancer, lymphoma, and melanoma." (PMID 34721660, 2021). "Future studies will be key to understanding how Dppa2/4, as well as other epigenetic priming factors, contribute to the initiation, development and metastasis of cancer." (PMID 33336687, 2020). "For example Dppa2/4 are frequently up-regulated in human cancers including lung, ovarian, colon, colorectal and gastric cancers, amongst others, likely due to the global demethylation that occurs in cancer cells, and are often associated with poor prognosis." (PMID 33336687, 2020). "Considering the importance of DPPA2 in developmental events and cancer, preparing a suitable platform to analyze DPPA2 roles in the cells seems to be necessary." (PMID 29849983, 2018). "DPPA2/4 serve as transcriptional regulators in both pluripotent and cancer cells." (PMID 38474345, 2024). "DPPA2 is specifically expressed in pluripotent cells and some cancer tissues." (PMID 34721660, 2021). "Furthermore, the produced cells with ectopic expression of target gene can be introduced to the mouse model to evaluate the tumorigenesis of these cancer cells in vivo, leading to an understanding of the biological importance of DPPA2 in tumorigenesis." (PMID 29849983, 2018). "Moreover, the introduction of its potential capacity into the mouse model to evaluate the tumorigenesis of these cancer cells in vivo leads to an understanding of the biological importance of DPPA2 in tumorigenesis." (PMID 29849983, 2018). "DPPA2 and DPPA4 are specifically expressed in pluripotent cells, cancer cells, preimplantation embryos, and germline cells." (PMID 38474345, 2024). "Moreover, cancer testis antigens, such as the MAGE family (especially MAGE-A4), LAGE, and NY-ESO1, are particularly expressed in DPPA2-positive NSCLC tumors." (PMID 36553636, 2022).
infection (3 papers, 2012 to 2025). The state of being infected such as from the introduction of a foreign agent such as serum, vaccine, antigenic substance or organism. "Genes in regions associated with odds of infection included DPPA2/DPPA4 (empirical P = 0.006), and SYTL3 (P = 0.051)." (PMID 23082221, 2012). "The locus most highly associated with odds of infection was a SNP in the DPPA2 (Developmental Pluripotency Associated 2) gene which was associated in both the all-breeds analysis (empirical P = 0.006) and in Polypays analyzed separately (empirical P = 0.048)." (PMID 23082221, 2012).
tumor (3 papers, 2011 to 2026). "Bioinformatics analysis revealed that CTCFL and DPPA2 were both upregulated in tumor tissues relative to the normal tissues in the TCGA-STAD dataset." (PMID 34721660, 2021). "While the function of DPPA2 remains obscure, expression of this gene is abnormal in various tumours." (PMID 21674058, 2011). "When exogenously overexpressed in NSCLC cells where they are not normally present, DPPA2/4 bind to and promote active chromatin states, resulting in an increase in in vivo xenograft tumor growth." (PMID 41862192, 2026).
DPPA2 also shares sentences with these, for which no sentence is quoted: depression (1 paper); lymphoma (1); melanoma (1); prostate carcinoma (1).